OR6C76 (olfactory receptor family 6 subfamily C member 76)
Description:
Odorant receptor.
Tractability: Antibody: UniProt places it where antibodies can reach, with medium confidence; UniProt predicts a signal peptide or a membrane-spanning region; its Gene Ontology location is reachable by antibodies, with medium confidence.
Gene: Protein-coding gene on chromosome 12 (55,426,254 to 55,427,192, forward strand). Ensembl gene ENSG00000185821.
Subcellular location: Cell membrane
Pathways (Reactome):
Sensory Perception: Expression and translocation of olfactory receptors
Gene Ontology:
Molecular function: olfactory receptor activity; G protein-coupled receptor activity
Biological process: detection of chemical stimulus involved in sensory perception of smell; G protein-coupled receptor signaling pathway
Cellular component: plasma membrane; membrane
Genetic constraint (gnomAD): Missense variants: 342 observed, 360.99 expected, observed/expected ratio (o/e) 0.95, 90% interval 0.87 to 1.04. Synonymous variants: 134 observed, 140.22 expected, observed/expected ratio (o/e) 0.96, 90% interval 0.83 to 1.1.
Homologues: Orthologues: rabbit OR6C76 (88% identical), mouse Or6c76 (87% identical), rat Or6c76b (86% identical), mouse Or6c76b (86% identical), rat Olr936 (84% identical), rat Olr1052 (84% identical). Paralogues in human: OR6C65 (74% identical), OR6C75 (73% identical), OR6C74 (72% identical), OR6C3 (71% identical), OR6C6 (70% identical), OR6C70 (70% identical), OR6C4 (69% identical), OR6C2 (68% identical), OR6C1 (68% identical), OR2AP1 (66% identical), OR6C68 (65% identical), OR6T1 (47% identical), and 6 more.